IFNG (interferon gamma)
Diseases named in the same sentence as IFNG in open-access papers (continued):
Sharing a sentence is not in itself a finding about the gene and the disease.
influenza (continued). "A similar pattern of proliferation induction was previously reported and was reported to coincide with the formation of influenza-specific IFNγ cytokine responses." (PMID 25946071, 2015). "GLA-SE has previously been shown to induce influenza-specific IgG2a titers and ex vivo IFNγ production as an adjuvant with trivalent inactivated flu vaccines." (PMID 25793508, 2015). "After sorting, culture and restimulation, influenza-specific IL-2+IFNγ- and IL-2+IFNγ+ cells maintained significantly biased ratios of IFNγ+ and IFNγ- cells." (PMID 24788814, 2014). "In contrast, heterogeneous expression of IFNγ in IL-2+ influenza-specific T cells appeared to be due partly to stable T cell subsets." (PMID 24788814, 2014). "In this model, we propose that the majority of the anti-influenza response comprises Tbet+ Th1 cells that stochastically produce all combinations of IL-2 and IFNγ when restimulated in vitro." (PMID 24788814, 2014). "Again, both groups of DCs were able to induce a comparable CD4 and CD8 T cell IFNγ response to influenza (p = 0.250 and p = 0.822 respectively)." (PMID 25475068, 2014). "This direct control of influenza infection is dependent on IFNγ, and it thought to be mediated through the induction of an antiviral state in the lung combined with the infiltration of innate immune cells." (PMID 24204639, 2013). "During influenza infection, alveolar macrophages are critical in clearing virus from the lungs and are key producers of IFNγ to stimulate the adaptive immunity." (PMID 23441208, 2013). "Consistent with the results from Elispot assays, FKDC were poor inducers of T cell IFNγ mRNA responses to influenza." (PMID 23390586, 2013). "There were striking increases in influenza-specific TNFα+, IFNγ+, and IL-2+ cells in the post-infection samples." (PMID 23526940, 2013). "Classically, NK cell effector functions include release of IFNγ and direct cytotoxicity to influenza-infected cells by granule exocytosis (e.g., granzyme B and perforin)." (PMID 23441208, 2013). "It is shown to regulate the immune response to intracellular bacterial infection through IFNγ modulation.The level of miR29 increases 50-fold in A549 cells in response to influenza infection, which leads to IFNλ and COX2 up-regulation." (PMID 24391886, 2013). "Such an anamnestic response in the number of influenza-specific IFNγ-producing cells in the blood has similarly been detected only at day 7 after the challenge of pigs with A/Sw/Indiana/1726/88 H1N1 swine influenza virus." (PMID 22427834, 2012). "Elevated levels of IFNγ have been shown in H5N1-infected individuals as well as 1918 influenza-infected macaques." (PMID 22808082, 2012). "We found that granzyme B was expressed in a greater proportion of the influenza reactive IFNγ positive CD8 T cells from older donors, however, as has been shown by others, granzyme B is also overexpressed in the total CD8 T cell population of 65+ donors." (PMID 21887299, 2011). "The precursor frequency of influenza-specific T cells was determined by an IFNg ELISpot assay on PBMC directly ex vivo." (PMID 21846352, 2011). "This and the fact that most IFNγ CD8 T cell responses to pH1N1 were under 0.1% in the Toronto cohort suggests that influenza-responsive CD8 T cell boosting from influenza infection is transient." (PMID 22132212, 2011). "As PBMC were stimulated for a maximum of 18 hours, influenza-specific IFNγ positive cells that we detect cannot come from a naïve population." (PMID 21887299, 2011). "We detected CD45RA on IFNγ-producing influenza-specific T cells after only 18h of stimulation, a timepoint which is too short for the expansion of influenza-specific T cells from naïve precursors." (PMID 21887299, 2011). "We have observed similar changes to the hematopoietic compartment during influenza and Mycobacterium tuberculosis infections (KM and GW, unpublished data), and similar IFNγ–directed alterations in hematopoiesis have been reported during malarial infection." (PMID 22194881, 2011).
influenza (continued). "Almost half of influenza-specific CD8 T cells produced only IFNγ However, a significant proportion of the T cells also made granzyme B and there were also small but detectable populations of T cells that produced other combinations of effector molecules." (PMID 22132212, 2011). "The finding that influenza-specific T cells in 65+ donors show signs of terminal differentiation was based on their functional ability to produce IFNγ upon restimulation." (PMID 21887299, 2011). "The GLA-SE adjuvanted Fluzone vaccine caused no adverse reactions, increased the induction of T helper type 1 (TH1)-biased cytokines such as IFNγ, TNF and IL-2, and broadened serological responses against drifted A/H1N1 and A/H3N2 influenza variants." (PMID 21060869, 2010). "More influenza-specific proliferation was observed in the cultures from WT mice than IL-6−/− mice and a higher percentage of these cells produced IFNγ." (PMID 18389078, 2008). "Finally, while the MHC-I peptide mix induced responses in all donors, specific peptides yielded more donor-specific responses, as evidenced by IFNγ secretion upon stimulation with specific influenza and SARS-COV-2 peptides." (PMID 41241731, 2025). "The results suggest that elevated levels of IL-4, IL-6, and IL-10, which are associated with Th2 cell activation, might be related to severe influenza, but the increased TNFα and IFNγ levels also need to be paid attention." (PMID 40558593, 2025). "Thus, we stimulated PBMC with either HA protein from influenza HS or inactivated whole virus from homologous A/Anhui/1/2013 (H7N9) influenza, and evaluated interferon γ (IFNγ) secretion as an indication of T-cell activation." (PMID 41444253, 2025). "Similarly, study participants who receive BCG before an influenza vaccination display increased hemagglutinin A titers and interferon gamma (IFN-γ) production." (PMID 39872813, 2025). "In one study, T cell-derived IFNγ following adenoviral infection leads to AM activation, innate training and protection from S. pneumoniae, while in another study influenza-induced T cell-derived IFNγ leads to AM dysfunction and impaired clearance of S. pneumoniae." (PMID 38236787, 2024). "Influenza-specific IFNγ responses to infection were then analysed using ELISpot." (PMID 37242338, 2023). "Influenza-specific IFNγ responses in lung MNCs were assessed in ferrets at day 14 post-infection." (PMID 37242338, 2023). "In each of the models, CD4+ T cells are recruited to the site of inflammation, and each type of infection is dominated by the corresponding TH cell subset, in numbers and proportions; Influenza by TH1 cells (IFNγ), N. brasiliensis by TH2 cells (IL-4, IL-13), and A. fumigatus by TH17 cells (IL-17)." (PMID 37696824, 2023). "In addition, the virosome influenza vaccine induced significant proliferation of CD3e+CD8α+IFNγ+ T cells in swine, similar to previous studies in vaccinated mice, and pigs inoculated with a nanoparticle-adjuvanted influenza vaccine." (PMID 37587490, 2023). "Also, they provided an explanation for the differential protective capacities of aaMAIT lineages against an extracellular bacterium, which are sensitive to IL-17, and influenza viral challenge of the lung, which responds to several cytokines including IFNγ." (PMID 37231163, 2023). "Similarly, some studies have indicated that peripheral NK cells are able to robustly trigger increased recall interferon-gamma responses for 6 months after influenza vaccination." (PMID 37849687, 2023). "The IFNγ SFC response remained significantly higher than the baseline value 6 months after the immunization when excluding the subjects situated in the highest quartile who had probably been exposed to influenza before vaccination (Day 1)." (PMID 35464450, 2022).
influenza (continued). "Indeed, influenza infection in BALB/c mice leads to a significant deterioration in the AMs number in an IFNγ-dependent manner, while the number of the infected C57BL/6 counterparts is not altered, but their phenotype is amended." (PMID 35062301, 2022). "Thus, we turned to an alternative approach, quantifying influenza-specific cells following challenge, that we had previously used in assessing IFNγ and IL-4 producing T cells." (PMID 36038596, 2022). "Additionally, IFNG transcripts increased significantly in these cells on D1 following influenza vaccination in COVR-M." (PMID 35233581, 2022). "The purpose of our study conducted over four consecutive influenza seasons was to compare antibody, IFNγ, IL-10, and GrB responses to vaccination among older adults randomized to receive the seasonal formulations of HD-SVV vs. SD-SVV, and a young adult control group who received SD-SVV." (PMID 35128529, 2021). "Similarly, peripheral blood mononuclear cells isolated from influenza-infected patients show selective defects in the production of TNFα and IFNγ after stimulation with heat-killed pneumococci." (PMID 33828999, 2021). "Vaccine-specific CD8 T cells produced predominantly IFNγ cytokines and displayed high Granzyme B activity, a phenotypic profile that was reported to be protective from not only symptomatic influenza infection, but also from severe complications in the 2009 H1N1 pandemic." (PMID 33922875, 2021). "The elderly tended to produce more IL-1β and IL-1RA, while young individuals could produce higher IFNγ amounts upon influenza stimulation." (PMID 34434199, 2021). "Similarly, no changes in antibody isotype frequencies have been observed with changes in IFNγ levels in response to influenza vaccine." (PMID 36845567, 2021). "Previous randomized studies comparing HAI antibody and IFNγ-mediated T cell responses to influenza vaccination in older adults have demonstrated the benefit of high-dose (HD) over standard-dose (SD) formulations of seasonal influenza split-virus vaccine (SVV)." (PMID 35128529, 2021). "IFNγ-deficient mice infected with lymphocytic choriomeningitis virus developed a severe CD8+ T-cell mediated immunopathology and responding CD8+ T-cells unable to produce IFNγ led to severe pulmonary immunopathology in influenza-infected mice." (PMID 33572859, 2021). "In addition, lung-resident memory CD8 T-cells, present in human lung tissue sections, contribute to interferon gamma (IFNγ) production in response to influenza." (PMID 34899695, 2021). "Also, it has been shown that levels of IL-2, IL-6, IL-18, TNFα, IFNγ, ET-1, sICAM-1, and sVCAM-1 are increased in influenza-infected MI patients." (PMID 33193350, 2020). "CD4 T cell-derived IFNγ was further found to be required for CD8 T cell entry into the lung and for CD103 upregulation on the CD8 T cells during influenza infection, suggesting that IFNγ could both indirectly and directly initiate CD8 TRM differentiation." (PMID 32971931, 2020). "Similarly, human PBMC stimulated with different inactivated influenza vaccines showed statistically significant differences in the numbers of activated IFNγ-producing cells depending on the amount of internal proteins contained in the vaccine." (PMID 32399058, 2020). "Also, the study showed that influenza vaccination reduces the levels of IFNγ, IL-2, and TNFα production and increases the levels of IL-4 in serum." (PMID 33193350, 2020). "Importantly, we have shown in in vitro experiments that there was an increase in the IFNγ:IL-10 ratio and GrB activity in response to influenza challenge when the TLR4 agonist GLA-SE was combined with SVV." (PMID 32399058, 2020). "Intra cellular cytokine staining revealed that the majority of CD8 influenza specific T cells in the BAL secreted IFNγ and TNF (39.9%), followed by IFNγ only producers (35.7%) and 14.5% produced all three cytokines (IFNγ, TNF, and IL-2), while CD4 T cells produced mainly IFNγ (49.3%)." (PMID 33193445, 2020).
influenza (continued). "Similarly, the expression of PHF11 was increased after influenza infection which can confirm its role in the diminution of pro-inflammatory chemokine and increase the IFNG due to the infection." (PMID 31665046, 2019). "Hence, production of factors such as STAT1 by the hNECs is also crucial in ensuring appropriate regulation of IFNγ-mediated expression of influenza response genes to modulate inflammation and to minimize damage." (PMID 31461941, 2019). "This phenotype, however, could be prevented by antibody-mediated IFNγ neutralization after influenza infection." (PMID 31744208, 2019). "However, IFNγ can also enhance influenza disease severity possibly through suppression of ILC2 function." (PMID 31612153, 2019). "When the frequency of CD4 T cells producing IFNγ, IL-2, or TNFα was individually quantified for each of the proteins, the pediatric population had a higher frequency of influenza-specific CD4 T cells producing TNFα compared to IFNγ across all conditions examined." (PMID 30692574, 2019). "In this study we have used commercially produced antibodies to ferret interferon gamma (IFN-γ) allowing us to reliably measure influenza-specific IFN-γ as a marker of the cellular immune response using both enzyme-linked immunospot (ELISpot) and enzyme-linked immunosorbent (ELISA) techniques." (PMID 30192789, 2018). "A similar relationship has been found for CD4+IFNγ− producing T cells specific to influenza." (PMID 29866115, 2018). "Analyzing CD8+ PBMC populations for prevalence of the CD38+HLA-DR+PD-1+ phenotype along with determining the profiles of IAV-peptide induced IFNγ production might be informative in understanding the outcome of severe influenza disease." (PMID 29483513, 2018). "In an elderly adult population, T cell IFNγ responses to influenza could distinguish between those protected by vaccination and those who subsequently developed influenza illness." (PMID 29866115, 2018). "The reasons for this dichotomy remain uncertain, but it has been speculated that the dose and strain of influenza, as well as the timing of IFNγ secretion, may determine the impact of IFNγ during influenza infection." (PMID 30410021, 2018). "Next, we determined whether STAT1 is altered due to increased levels of IFNγ in Stat2−/− mice during influenza-bacterial super-infection." (PMID 30337919, 2018). "Lower IFNγ:IL-10 ratios and levels of the cytolytic mediator, granzyme B, in influenza-challenged peripheral blood mononuclear cells (PBMC) correlate with increased risk of influenza in vaccinated older adults." (PMID 26941738, 2016). "Greater IFNγ response to influenza promotes viral clearance and may be one pathway by which exercise may have improved the rate of viral clearance." (PMID 26110868, 2015). "In addition to mediating IL-17 and IL-10 responses, it has been reported that IL-27 signaling affects IFNγ production by CD8+ cells during primary influenza infection." (PMID 25651926, 2015). "The two influenza-specific IFNγ+ populations expressed similarly high amounts of IFNγ on restimulation, whether cultured in Th1 or Th2 differentiation conditions." (PMID 24788814, 2014). "T cells expressing IFNγ are critical to control and clear influenza." (PMID 25358535, 2014). "We therefore tested IL-2 and IFNγ expression in the Th1-dominated influenza-specific response." (PMID 24788814, 2014). "However, when DCs are co-cultured with antigen such as influenza as it was in this culture, not only are we able to detect antigen specific proliferation but we are now able to detect IFNγ within that subset." (PMID 25475068, 2014). "This IFNγ+ bias is particularly clear in the response to long-circulating influenza strains, whereas a new pandemic influenza strain induced a mixed influenza-specific response including both IL-2+IFNγ- and IL-2+IFNγ+ cells (abbreviated 2+γ- and 2+γ+, respectively)." (PMID 24788814, 2014).
influenza (continued). "Furthermore T cell responses are better correlates of vaccine protection in the elderly, with the ratio of IFNγ to the immunosuppressive cytokine IL10 better correlating with protection against influenza than serum antibody titers." (PMID 24204639, 2013). "The IL-2+ producing T cell bias was not due to overlap of the IL-2+ T cells with T follicular helper (Tfh) cells, as the majority of both IFNγ+TNFα+ and IFNγ−IL-2+TNFα+ influenza-specific cells responding to CA/09 and NC/99 were found within the CXCR5− CD4 T cell population." (PMID 23526940, 2013). "Similarly, when memory T cell responses to influenza were measured by IFNγ Elispot assay, FKDC were found to be markedly less stimulatory than untreated DCs." (PMID 23390586, 2013). "Interestingly, in our transfer system PD-L1−/−-derived iNKT cells produced high levels of interferon-gamma whereas PD-L2−/−-derived iNKT cells produced high amounts of interleukin-4 and 13 suggesting a role for these cytokines in sensitivity to influenza." (PMID 23555047, 2013). "This could represent an exciting development based on in vitro studies that established that IFNγ has an anti-viral role against human influenza, and IgG2a is more effective than IgG1 in preventing intracellular virus replication." (PMID 24204639, 2013). "We conclude that i.n. vaccination with FluGEM-A, in addition to activation of humoral immune response, and unlike i.n. vaccination with TIV, stimulates cellular responses in human subjects, as shown by a vaccine-induced increase in the number of influenza-specific IFNγ-producing PBMCs." (PMID 24062748, 2013). "We detected a significant amount of influenza-driven IFNγ-producing cells in PBMC isolated from pigs vaccinated with the adjuvanted split vaccine, which peaked at day 7pv (46±20 pg/ml, adjusted P<0.01, n = 3) and subsequently remained at a low level until day 28pv." (PMID 22427834, 2012). "Plasma levels of IL-6, IL-8, MCP-1 and IFNγ were significantly increased in swine H2N3 compared to human H2N2 infected animals supporting the previously published notion of increased IL-6 levels being a potential marker for severe influenza infections." (PMID 22808082, 2012). "In addition, intracellular staining of interferon-gamma (IFN-γ) demonstrated the induction of T-cell responses upon vaccination and subsequent influenza challenge." (PMID 21850242, 2011). "Among the 28 vaccines, most subunit vaccines and all viral vaccines, including three Influenza vaccines (Fluarix, Fluzone, and Vaxigrip), are not directly associated with IFNG; however, they are frequently associated with IFNA1 (IFN-alpha 1)." (PMID 21624163, 2011). "Among all of the tested conditions, DCs that were generated in CellGro and activated using Poly I:C were the most efficient in inducing influenza MP-specific T cells based on frequency and function, which were determined by assessing influenza MP tetramer staining and IFNγ production, respectively." (PMID 22208910, 2011). "Although most donors had pre-existing influenza reactive T cells as measured by IFNγ production, older donors had smaller populations of influenza-responsive T cells than young controls and had lost a significant proportion of their CD45RA-negative functional memory population." (PMID 21887299, 2011). "Hence, CD8 T cells with high levels of IL-18Rα may contribute to influenza disease severity through pathologic secretion of IFNγ." (PMID 41285788, 2025). "Moreover, stimulation with the influenza vaccine or CpG resulted in increased IL-6 levels in the culture supernatants, suggesting innate cell activation as well as IFNγ and TNF which may indicate Th1 helper responses." (PMID 39355250, 2024). "Thus, GPR56+ CD8 EM cells could be a potential source of elevated IFNγ production in COVR-M following influenza vaccination." (PMID 35233581, 2022).